TERT (telomerase reverse transcriptase)
Diseases named in the same sentence as TERT in open-access papers (continued):
Sharing a sentence is not in itself a finding about the gene and the disease.
tumor (continued). "Mutations in ARID1A (p = 0.0205), ARID2 (p = 0.0207), BRAF (p = 0.023) SMARCA4 (p = 0.015), TERT (p = 0.0041), and IDH1 (p = 0.0041) were significantly exclusive to BM while the same variants remained undetected in the corresponding extracranial tumor tissues." (PMID 33578810, 2021). "We also found TERT-telomeric signals related to correlation with tumor differentiation and stage progression." (PMID 33946181, 2021). "Taken together, these findings indicated that the synergistic co-overexpression of TERT, E2F1, and MYC in PCa is strongly associated with poor prognosis, tumor progression, metastasis, and patient survival." (PMID 34858826, 2021). "Mutational status in TERT and PLEKHS1 promoters and GPR126 intron 6 was analyzed in tumor DNA derived from 164 patients with UTUC using Sanger sequencing." (PMID 34093793, 2021). "Among 60 PTCs, 41 primary tumor tissues (68.3%) harbored the BRAF mutation, while 2 (3.5%) harbored TERT promoter mutation." (PMID 33915745, 2021). "hTERT is the functional subunit of the enzyme TERT and it is crucial to erase senescence and immortalize tumor cells." (PMID 33909215, 2021). "In agreement with telomerase reactivation, an important prerequisite for achieving immortalization, we found a higher expression of h-TERT mRNA levels in DHSF-BR16 cells compared to primary tumor and normal tissues." (PMID 33863935, 2021). "DN‐TERT was overexpressed at similar levels as wild‐type TERT and also increased miR500A promoter activity, miR500A transcript levels and tumour invasiveness in vivo." (PMID 33713376, 2021). "Genomic testing revealed increased tumor mutational burden and alterations in NF1, BRAF, CDKN2A/B, TERT." (PMID 34926265, 2021). "TERT promoter mutations promote telomerase activation; in addition, a synergistic effect with driver mutations, mainly BRAF, in promoting tumor aggressiveness has been demonstrated." (PMID 33799953, 2021). "We did not observe any statistically significant correlations between AR and TERT abundance, or tumour TL." (PMID 34824250, 2021). "A statistically significant difference was also performed between tumour (0.00576 ± 0.00164) and healthy tissue (0.00079 ± 0.000385) in TERT expression (Z = 2.19; p = 0.028)." (PMID 33530592, 2021). "Two hotspot mutations in the TERT promoter region, −124 C>T (C228T) and −146 C>T (C250T), were observed in 57 (27.8%) HCC samples but in only one (1.0%) non-tumor sample (p < 0.001)." (PMID 33946181, 2021). "In the past two decades, it has also become apparent that TERT is expressed at every stage of the cancer process, from the incipient cancer stem/tumor initiating cell through to the metastatic cancer cell, playing an essential role in each stage." (PMID 32630460, 2020). "The distribution of SFRP1-methylated and -unmethylated cases in relation to the tumor type clearly showed that most of the HCC/TLCT samples displayed an enrichment of SFRP1 DNA methylation and that all tumors with a TERT mutation were SFRP1-methylated." (PMID 32189106, 2020). "Because of its expression during all stages of tumor differentiation, TERT remains an important immunological target for immunotherapy." (PMID 32630460, 2020). "Haploinsufficiency of TERT in tumor cells is sufficient to result in telomere attrition and growth retardation in vitro." (PMID 31963842, 2020). "Here we report an efficient Cas9 editing strategy on the TERT gene and its efficacy in suppressing tumor cell growth in vitro and in vivo." (PMID 31963842, 2020).
tumor (continued). "Feline oral squamous cell carcinoma (FOSCC) is a malignant tumor with highly invasive phenotype; however, studies on telomerase activity, TERT, and MMPs expression are scarce." (PMID 32292795, 2020). "Significant high expression of TERT was detected in tumor tissues compared to paired ANT, which was consistent with our analysis from database." (PMID 33061812, 2020). "Nonetheless we found that circulating TERT levels at T2 and ΔTERT levels were predictive of tumor response and prognostic of disease outcome." (PMID 33113831, 2020). "The TERT prediction analysis shows that tumor information-measure of correlation and upper-left edema bounding box are the most frequently selected features." (PMID 32111869, 2020). "We also mapped autoepitopes of TERT lying outside rtTERT and demonstrated that T-helper cell response against such epitopes promotes tumor growth." (PMID 32570805, 2020). "In this study we designed over twenty DNA-encoded genetic adjuvants and tested their ability to enhance antigen-specific T cell responses to vaccination against two different tumor-associated antigens, STEAP1, and TERT." (PMID 32161596, 2020). "To further investigate the TERT protein expression in RCC, we examined the protein expression of TERT by IHC in RCC tumor tissues and adjacent normal tissues (ANT)." (PMID 33061812, 2020). "TERT activity is an important mechanism for cancer to escape apoptosis and a promising therapeutic target for cancer, as it is highly expressed in most tumor cells and hardly expressed in normal cells." (PMID 32455687, 2020). "Overexpressed in tumors and immunogenic in subjects controlling tumor growth, TERT presents as an attractive target of therapeutic cancer vaccines." (PMID 32570805, 2020). "TERT promoter mutation tended to present in older patients (SMD 1.25; 95% CI, 0.66–1.85; P < 0.05) and with larger tumor size (SMD, 0.60; 95% CI, 0.27–0.94; P < 0.05)." (PMID 31655978, 2020). "Importantly, the present data was able to show the effect of TERT mutation C228T on the 5-year disease-free survival, which was 20.0% for patients harboring this mutation vs. 63.0% for patients without this mutation, being therefore associated with an increased risk of tumor relapse." (PMID 32850388, 2020). "NCOA3 promotes HCC cell growth and tumor progression in vitro and in vivo through upregulating the TERT signaling." (PMID 33239622, 2020). "The RB-E2F axis is one of the critical tumor-suppressor/oncogene pathways involved in regulating TERT expression." (PMID 32429447, 2020). "TERT mRNA expression was more frequently detected in the more aggressive tumours, being the highest levels of expression found in the aggressive variants of PTC and in PDTCs." (PMID 32659948, 2020). "In contrast, the majority of cancers overexpress telomerase: in a systematic analysis of 31 tumour types, over-expression of TERT was identified in 73% of all cancers." (PMID 32375866, 2020). "In preclinical models, immunization of mice with DCs transfected with TERT mRNA efficiently triggered CTLs competent to recognize and eliminate both murine and human tumor cells." (PMID 32806719, 2020). "To further explore the association of the protein expression of PUF60 and TERT, we conducted the Pearson correlation analysis of PUF60 and TERT expression in RCC tumor tissues, and a significant correlation was observed (r=0.5182, P<0.0001)." (PMID 33061812, 2020). "TERT promoter mutations are found in 7.5% of PTC and 17.1% of FTC and are associated with tumor dedifferentiation from DTC to PDTC (29%) or ATC (33.3%)." (PMID 32668761, 2020). "It is highly likely that TERT homeostasis is also tuned by these functions within a given tumor type and microenvironment, and by related metabolic alterations that need to be preserved." (PMID 32204305, 2020).
tumor (continued). "Contrary to mammals where TERT expression and telomerase activity are restricted to germ line cells, stem cells and tumor cells, fish including rainbow trout show a high activity of telomerase in somatic tissues regardless of the age of the studied specimens." (PMID 32751994, 2020). "Alterations found to be responsible for TMM in tumor cells include TERT rearrangement, somatic mutations of the TERT promoter, ALT, epigenetic changes, and amplification of TERT gene." (PMID 32825087, 2020). "Thyroid samples adjacent to malignant tumours that present lymphocytic infiltration had higher levels of TERT mRNA expression than the tumour by itself and then thyroid adjacent to malignant tumours without lymphocytic infiltration." (PMID 32659948, 2020). "The IDH1, TERT, and 1p/19q; and IDH1 and MGMT molecular groups were independently associated with tumor growth." (PMID 32388499, 2020). "This is because tumor cells, up to 90% in all cancer types, activate TERT/telomerase to achieve immortality." (PMID 31963842, 2020). "In pRCC2 tumors, we observed a SMARCB1 driver mutation in one pRCC2; TERT promoter in two pRCC2; SETD2, PBRM1 and NF2 in one pRCC2 tumor each." (PMID 32555180, 2020). "It is likely that RAS mutations work cooperatively together with TERT promoter mutations through the activated PI3K pathway, to promote aggressive tumor characteristics, but this needs to be investigated further." (PMID 32751138, 2020). "The 124C>T in TERT gene would increase telomerase promoter activity and lead to the overexpression of TERT and preservation of telomere, enabling tumor cells to proliferate and evade senescence eventually." (PMID 32855962, 2020). "Many literatures reported that the activation of TERT was the main mechanism for tumor cells to escape aging and obtain malignant proliferation." (PMID 33041323, 2020). "Conversely, one tumor pair shared missense mutations in three genes (EMSY, SMAD4, and POM121L12) and gene copy number amplification of three genes (SDHA, TERT, and EGFR)." (PMID 33139840, 2020). "In a systematic analysis of TERT gene amplification based on 31 tumor types from 6835 patients, TERT amplifications were observed in 4% of tumors." (PMID 32121056, 2020). "HBV DNA is integrated near TERT, which activates expression of the TERT gene to promote the conversion of tumor cells and provoke HCC." (PMID 33044946, 2020). "Molecular groups of IDH1, TERT, and 1p/19q; and IDH1 and MGMT were independently associated with tumor growth." (PMID 32388499, 2020). "TERT-specific CD4 T cells would nevertheless enable other responses by providing an initial attack on tumor cells and/or helping the expansion of CD4 and CD8 T cells with different tumor antigen specificities (epitope spreading)." (PMID 32630460, 2020). "For example, the combination of TERT mutation and a BRAF or RAS mutation within the same tumor is associated with low degree of differentiation, aggressive behavior and high risk of recurrence and mortality." (PMID 33114365, 2020). "From these data, we inferred the expected number of TERT events in each tumour type and found that about 263 (95% confidence interval 232–295) TERT hotspot mutations were probably missed owing to a lack of detection sensitivity." (PMID 32025015, 2020). "Telomerase reverse transcriptase (TERT) is a conserved self-tumor antigen which is overexpressed in most tumors and plays a critical role in tumor formation and progression." (PMID 32630460, 2020). "We showed that atorvastatin treatment decreased the levels of IL-6, p-STAT3, and TERT but increased β-gal expression and SA-β-gal activity in tumor lesions." (PMID 32257389, 2020).
tumor (continued). "In many cancers, the full length TERT transcript (α+β+) correlated with tumor development and shorter survival in patients." (PMID 33329574, 2020). "Only 10% of human tumors maintain telomeres by ALT and 90% use reactivation of TERT, which reveals the importance of replicative senescence in tumor suppression." (PMID 33257697, 2020). "In the malignant tumours, TERT mRNA level of expression in WDTC were also different when grouped by tumour size at diagnosis (One-way ANOVA p = 0.0209)." (PMID 32659948, 2020). "This motivates intensive efforts to create a wider panel of efficacious TERT-based tumor vaccines as well as delineate the immune mechanism(s) underlying their efficacy." (PMID 32570805, 2020). "These enriched functions in tumors of Group B reflected the impact of genetic variation, which included TERT promoter mutation, EGFR amplification, and combined 7 + /10−, on the tumor with similar histologic features." (PMID 33195221, 2020). "Most tumor cells activate TERT as a mechanism for preventing progressive telomere attrition to achieve proliferative immortality." (PMID 31963842, 2020). "After adjustment for WHO grade, ATRX, Ki67 and TERT, the molecular groups of IDH1 and MGMT were independently associated with tumor growth." (PMID 32388499, 2020). "It needs to be taken into consideration that these clinical features are dependent on each other, since the tumor manifests at older ages in the HCC/TLCT group, which is furthermore characterized by frequent TERT mutations." (PMID 32189106, 2020). "TERT promoter mutations tended to present in older patients (SMD, 1.14; 95% CI, 0.70–1.59; P < 0.05) and with larger tumor size (SMD, 0.66; 95% CI, 0.40–0.92; P< 0.05)." (PMID 31655978, 2020). "These genetic alterations did not confer a worse OS in patients with higher grade T classification (T>0), tumor grade or ARID2, TERT mutations." (PMID 32850303, 2020). "TERT methylation was measured to be 1.2% to 76.6%, with an average methylation of 21% in females (n = 45) compared to 28.2% in male (n = 73) tumor samples (p = n.s.)." (PMID 32605217, 2020). "We then detected the NCOA3 and TERT protein expression in the tumor and peritumoral tissues of 30 HCC patients from the Sun Yat-Sen University Cancer Center." (PMID 33239622, 2020). "Here, we have identified nuclear receptor coactivator-3 (NCOA3) as a new modulator of TERT expression and tumor growth in HCC." (PMID 33239622, 2020). "ChIP-Seq data also demonstrate that in SK-N-SH or HEPG2 tumor cells GABPA is present at the TERT promoter region." (PMID 33257697, 2020). "Independent to direct T cell engagement, vaccine formulation with Flt3L was associated with enhanced T cell responses to both tumor antigens by >2-fold (STEAP1: 2.67 fold; TERT: 2.7 fold)." (PMID 32161596, 2020). "BIBR1532 down-regulates cMyc expression in tumor cell lines through the perturbation of regulatory cancer-related microRNAs (miRNA), resulting in the repression of TERT expression and subsequent inhibition of its extra-telomeric functions." (PMID 33553285, 2020). "Degraded fragments of TERT expressed on the surface of tumor cells are recognized by the immune system and induce cellular immune response resulting in a partial control of tumor growth." (PMID 32570805, 2020). "Altogether, these data pointed at inability of TERT2-specific T cells to eradicate TERT-expressing (tumor) cells and limit tumor growth and even indicated a promotion of tumor growth by TERT2-specific CD4+ cells." (PMID 32570805, 2020). "Through the present work, we further demonstrate that TERT haploinsufficiency is a sufficient dose to result in tumor suppression in vitro and in vivo." (PMID 31963842, 2020). "Currently, the TERT genotype has been prevailingly determined by sequencing tumor samples, which can only be obtained postoperatively." (PMID 32509858, 2020).
tumor (continued). "In this scenario, TERT reactivation regenerates telomeres sufficiently to maintain them above the critical threshold and to stabilize the tumor genome." (PMID 32204305, 2020). "We also showed that hotspot mutations of TERT promoter and FGFR3 are frequently identified in tumor tissues of Japanese UBC patients consistent with those in previous report in Western countries." (PMID 32509577, 2020). "Through the present work, we confirmed that TERT is a valid target to suppress tumor cell survival disruption." (PMID 31963842, 2020). "Our results showed that both NCOA3 and TERT had higher expression in the tumor tissues, and the expression of NCOA3 and TERT were, respectively, elevated in 88% (26/30) and 78% (23/30) of the HCC tissues." (PMID 33239622, 2020). "Early experiments with TERT null mutant mice resulted in contradicting data regarding the tumor suppressor effect of telomere shortening." (PMID 33257697, 2020). "Another possible TERT transcription regulation activity that supports tumor metastasis is promoting epithelial-to-mesenchymal transition (EMT)." (PMID 32599885, 2020). "We next tested if TERT haploinsufficiency has effects on tumor cell survival in vivo using a tumor xenotransplant model in nude mice (n = 4)." (PMID 31963842, 2020). "TERT is also expressed in circulating tumor cells (CTC) shed from the primary tumor and is required for epithelial-mesenchymal transition (EMT)." (PMID 32630460, 2020). "TERT mRNA levels of expression were also significantly different when considering the tumour size (ANOVA p = 0.0008)." (PMID 32659948, 2020). "This underscores the key role of telomere stabilization in the process of transformation, as well as the necessity of maintaining an exquisitely balanced TERT homeostasis to achieve tumor cell selection, adaptation, and sustainability." (PMID 32204305, 2020). "The RB-E2F pathway is one of the critical tumor-suppressor/oncogene pathways involved in regulating TERT gene expression." (PMID 32429447, 2020). "Numerous studies have shown that telomerase activity is increased in a variety of tumor cells and that increased telomerase activity is associated with increased copy number of telomerase core members TERC and TERT genes." (PMID 33256840, 2020). "A previous study revealed that genetic alternations such as TERT mutations, BRAF V600E mutations, and RET/PTC rearrangement all contributed to the tumor proliferation and metastasis." (PMID 31583243, 2019). "The chloroform extract of AS, butylidenephthalide (BP), inhibits the proliferation of human GBM through the down-regulation of TERT and the consequent reduction in TA, leading to tumor senescence." (PMID 30625996, 2019). "One of the critical mechanisms of these BP-wafers was the reduction in TERT mRNA expression, which leads to tumor senescence." (PMID 30625996, 2019).